CD4 (CD4 molecule)
Diseases named in the same sentence as CD4 in open-access papers (continued):
Sharing a sentence is not in itself a finding about the gene and the disease.
AIDS (continued). "The 12-month AIDS risk, which is calculated using the CD4 lymphocyte count and the age, was a strong predictor of mortality, suggesting that this parameter could be useful for resource-limited settings." (PMID 24688879, 2014). "A rapid increase of CD4 cells is important in the light of the fact that a significant proportion of patients continue to present for therapy when advanced immunodeficiency is present and their immediate risk of AIDS and death is high." (PMID 24498036, 2014). "However, when further divided, absolute CD4 counts <200 at six months were associated with approximately 2.0- to 3.0-fold increase in the risk of a new AIDS-defining condition, compared to a CD4 count ≥200 cells/ml." (PMID 24594114, 2014). "Acquired immunodeficiency syndrome (AIDS) patients have reduced CD4+ T cells and the incidence of hypertension has been reported to be lower in AIDS patients than in HIV-negative participants." (PMID 25136585, 2014). "Furthermore, the excluded variables were already being controlled for indirectly; in particular, previous AIDS diagnosis was partly captured by the CD4 count at HAART initiation variable (i.e., AIDS is usually associated with lower CD4)." (PMID 24489902, 2014). "Furthermore, it results in a significant loss of CD4+ T cells in peripheral blood that eventually leads to the symptomatic stage of infection (i.e. AIDS)." (PMID 25028990, 2014). "Indeed, HIV transmission mode is an important predictor of prognosis in HIV-infected persons and different studies showed that IDVU is strongly associated to AIDS events even with CD4 counts >500 mm3." (PMID 24760049, 2014). "Acquired immunodeficiency syndrome (AIDS) is characterized by progressive depletion and dysfunction of CD4 T cells, associated with the development of opportunistic infections and neoplasms." (PMID 25225815, 2014). "In the early 1980s, HIV was discovered as the cause of the life-threatening acquired immunodeficiency syndrome (AIDS), and soon CD4 was identified as the primary receptor of HIV." (PMID 25087847, 2014). "Reduced initial CD4 cell count was strongly associated with AIDS and death in adjusted analysis." (PMID 25523753, 2014). "It is unlikely, however, that elite control is an indefinite state, and that the few HIV-positive individuals who spontaneously control HIV replication may eventually need treatment or develop AIDS given the on-going, albeit slow, CD4 cell loss." (PMID 24489776, 2014). "Chronic HIV infection causes gradual depletion of the CD4+ T cell pool and thus progressively compromises the hosts immune response to opportunistic infections, leading to Acquired Immunodeficiency Syndrome (AIDS)." (PMID 24829609, 2014). "However, in approximately 40% of subtype B HIV-1 (B-HIV) infections, viruses that utilize CXCR4 (R5X4 and X4 viruses) emerge, which is associated with rapid CD4+ T-cell decline and onset of acquired immunodeficiency syndrome (AIDS)." (PMID 25313689, 2014). "In a sub-analysis of ART naïve patients who achieved complete virological suppression within one year (21 events only), ID was marginally significantly associated with non-AIDS even after controlling for current CD4 (aRR for ID 4.54, 95% CI 0.97–21.2, p = 0.054)." (PMID 24498036, 2014). "Loss of CD4 T cells below 750/mm3 is associated with AIDS-defining events in other patients." (PMID 24465584, 2014). "Since HIV infection leads to a damage of CD4+ T cells, we thought to investigate whether HIV-infected patients with AIDS and severely reduced CD4 T cell counts continued to suffer from IgE-associated allergic symptoms and to produce allergen-specific IgE." (PMID 24896832, 2014). "IDU transmission group, age over 50, HIV RNA over 10,000 copies/ml, CD4 cell count below 500/mm3, AIDS stage, hepatitis C co-infection and cardiovascular risk factors such as diabetes, high blood pressure, and tobacco use were all significatively associated with the occurrence of severe morbidity." (PMID 25076050, 2014).
AIDS (continued). "In patients with 350 CD4 cells/mm3 or more, the decision to begin therapy should be individualized based on the presence of comorbidities, risk factors for progression to AIDS and non-AIDS diseases, and patient readiness for treatment." (PMID 23874985, 2013). "Moreover, it became apparent from the first full clinical description of AIDS in 1981 that the salient feature underlying the disease is a specific depletion of CD4 T-helper lymphocytes." (PMID 23692808, 2013). "In one study of HIV-1-infected women, HCV-viremic compared with HCV-uninfected women had high levels of activated CD8 T cells associated with incident AIDS, and AIDS in both groups was associated with CD4 activation, while suppression of HCV with therapy reduces activation." (PMID 26316953, 2013). "The rise of non-AIDS-defining conditions as a cause of death followed an incremental increase in CD4+ T cell counts at the time of death in this study (from 59/mm3 in 1996 to 287/mm3 in 2004), and non-AIDS deaths were associated with higher CD4+ T cell counts at the time of ART initiation." (PMID 24260125, 2013). "This hypothesis is supported by the fact that, in our patient set, male AIDS patients have significantly increased risk of death from cryptococcal meningitis despite higher CD4+ T lymphocyte counts on admission to the hospital, (personal communication)." (PMID 23741297, 2013). "In this treatment-naïve population, those who initiated therapy with CD4 counts below 200 more than quadrupled the risk of the composite non-AIDS endpoints (major cardiovascular diseases, liver cirrhosis and non-AIDS malignancies) than those who initiated treatment with CD4 counts >500 cells/μl." (PMID 23767762, 2013). "Similarly, primary CMV infection in HIV patients, even with CD4 T cell counts >100 cells/μl, correlates with increased risk for earlier onset of AIDS." (PMID 23717308, 2013). "Our secondary objective was to determine if CD4:CD8 ratio could have an additional role as a prognostic marker for improved health outcomes with respect to developing AIDS-defining illness or death from all causes." (PMID 24204912, 2013). "The risk for MAC in AIDS patients is greatest in those with severely depressed CD4 count." (PMID 24303220, 2013). "Human immunodeficiency virus type 1 (HIV-1), the causative agent of acquired immunodeficiency syndrome (AIDS) in humans, infects CD4+ T cells as well as macrophages and dendritic cells by binding to its primary receptor, CD4, and a co-receptor, usually CCR5 or CXCR4." (PMID 23301078, 2013). "Idiopathic CD4 lymphocytopenia (ICL) is a rare immune deficiency characterized by a protracted CD4+ T cell loss of unknown etiology and by the occurrence of opportunistic infections similar to those seen in AIDS." (PMID 23383227, 2013). "Finally, TB is associated with increased systemic viral replication and heterogeneity, decreased CD4+ cell counts, more rapid progression to acquired immune deficiency syndrome (AIDS), and increased mortality." (PMID 24282561, 2013). "The risk for MAC infection in AIDS patients is greatest in those with severely depressed CD4 count." (PMID 24303220, 2013). "Viral load and CD4 measurements when done together will help in further identifying and characterizing immuno-virologic discordance which has been associated with increased risk of AIDS events and mortality." (PMID 23452915, 2013). "Indeed, AIDS diagnosis at enrollment and lower CD4 cell count were significantly associated with a higher hazard of death from AIDS-related causes in the multivariate analysis." (PMID 23577074, 2013). "In time-updated analyses, AIDS and current CD4 cell counts of less than 200 cells/mm3 were associated with an increased incidence of ICU admission while receipt of combination antiretroviral therapy (cART) was associated with a reduced incidence of ICU admission." (PMID 23331544, 2013).
AIDS (continued). "Moreover, syncytia formation has been linked to HIV pathogenesis and progression to AIDS, with syncytia inducing (SI) phenotype viruses appearing later during the disease and associated with rapid CD4+ T cell decline." (PMID 23202514, 2012). "The immunological patterns associated with AIDS presentation independently of demographic factors were of course lower CD4+% T cells (AOR 0.996 for each unit more, 95%CI 0.993–0.998, P = 0.008) but also higher CD38+CD8+% (AOR 1.049 for each unit more, 95%CI 1.004–1.096, P = 0.033)." (PMID 22110905, 2012). "However, HIV variants that do not require CD4 for the infection are sometimes isolated from AIDS patients though the infectivity of CD4-independent variants is much lower than that of CD4-dependent viruses." (PMID 23304142, 2012). "Previous studies have shown an increased risk of AIDS or death with lower time updated CD4 cell count in untreated patients and in treatment experienced patients, and with lower CD4 cell count at the start of treatment or after 6 mo of treatment in treatment-naive patients." (PMID 22448150, 2012). "At certain CD4 levels, the risk for AIDS-indicator diseases increases." (PMID 23882358, 2012). "Furthermore, CD4+ T-cell responses targeting Gag and Env-specific epitopes were associated with spontaneous control of viral replication and progression to AIDS, respectively." (PMID 23028895, 2012). "Most individuals infected with human immunodeficiency virus-1, in the absence of antiretroviral therapy, exhibit persistent virus replication and declining CD4+ cell numbers, and progress to acquired immunodeficiency syndrome within 10 years of infection." (PMID 22967353, 2012). "The CD4 cell count is the strongest predictor for risk of death and AIDS at the time of initiating therapy, initiating highly active antiretroviral therapy (HAART) at higher CD4 cell counts has been demonstrated to “the risk of death, opportunistic infections and non-HIV related comorbidities”." (PMID 23056931, 2012). "Of these, bystander apoptosis appears to encompass an explanation for most of the phenomenon observed during HIV infection that lead to progression to AIDS and remains one of the leading hypothesis for CD4+ T cell loss." (PMID 23202514, 2012). "Using data from the Collaboration of Observational HIV Epidemiological Research Europe, Jim Young and colleagues show that in successfully treated patients the risk of a new AIDS event or death follows a CD4 cell count gradient in patients with viral suppression." (PMID 22448150, 2012). "However the association between CD4 cell count and AIDS or death appears much more stable across cohorts, consistent with our analytic approach where each cohort had a separate baseline hazard but covariate effects were assumed to be the same in each cohort." (PMID 22448150, 2012). "In multivariate analysis, however, besides declining CD4+ cells, the main association with AIDS presentation was the presence of higher immune activation, consistent with the notion that in AIDS patients a profound immunodeficiency strongly correlates with generalized immune activation." (PMID 22110905, 2012). "Furthermore, the independent association between HBV vaccine responses and AIDS/death was observed in the subset of those with CD4 count ≥500 cells/mm3." (PMID 22457767, 2012). "During human (HIV) and simian (SIV) immunodeficiency virus infection, loss of CD4+ T cells and progression to AIDS are associated with a decline in antibody titers to the viral Gag protein, while antibodies to the Env protein remain high, suggesting a T cell independent antibody response to Env." (PMID 22583867, 2012). "Clinical studies have demonstrated that sustaining viral suppression and maintaining higher CD4 count, mostly as a result of effective combination antiretroviral therapy, delay or prevent some AIDS/non-AIDS–defining complications, such as HIV-associated kidney disease." (PMID 21455432, 2011).
AIDS (continued). "Furthermore, these data support the view that the persistence of HIV-1 gp120 in lymphoid tissues during early infection is associated with dysregulation of T cell function beyond CD4 T cell depletion that is emblematic of HIV/AIDS." (PMID 21483689, 2011). "In our study, however, four out of five AIDS-defining events registered after the first 60 days of HIV infection were associated with CD4 counts greater than 200 cells/mm3, thereby highlighting the need to consider opportunistic infection even in patients with moderate immune deficiency." (PMID 21831310, 2011). "We found that the VL parameters predicted different aspects of CD4 count recovery even after accounting for factors that we found to be highly predictive of AIDS risk, including prior history of AIDS, nadir CD4, age at HAART initiation and time to VL suppression." (PMID 21625477, 2011). "Factors identified as associated to MTCT were: low CD4 cell counts, elevated viral loads, maternal AIDS, shorter periods receiving HAART, other conditions (anemia, IUGR (intra uterine growth restriction), oligohydramnium), coinfecctions (CMV and toxoplasmosis) and the occurrence of labor." (PMID 22129112, 2011). "We next determined whether the VL kinetic and other parameters that were included in the models to assess AIDS risk during HAART also associated with the rate of CD4 gain." (PMID 21625477, 2011). "Also, our inclusion of chronic symptoms associated with HIV infection in addition to AIDS defining events and low CD4 T cell counts further increased this already large number of late presenters." (PMID 20626905, 2010). "This may account for the loss of CD4+ T cells seen during progression of HIV-1 infection toward AIDS." (PMID 21085612, 2010). "The acquired immune deficiency syndrome (AIDS) causing virus HIV-1 uses its coat glycoprotein, gp120, to bind CD4 on the surface of leukocytes, including T helper cells and dendritic cells." (PMID 22069653, 2010). "The combination of their loss with the loss of CD4+ LPL suggests that multiple immunologic factors may be involved in AIDS-associated enteropathy." (PMID 20085648, 2010). "During late-stage AIDS, declining CD4 counts lead to immune deficiency and reduced selection pressure, allowing viral population expansion that may alter the distribution of sequence variants." (PMID 21156070, 2010). "Constant virus replication in CD4 T lymphocytes initiates progressive immune defects and finally, after 6 to 10 years, results in acquired immunodeficiency syndrome (AIDS) and death." (PMID 20642814, 2010). "Moreover, these allelic forms of TRIM5 were associated with the extent of loss of central memory (CM) CD4+ T cells and the rate of progression to AIDS in the infected monkeys." (PMID 20107597, 2010). "High-level IFN-α was hard to control in rhesus macaques, which could cause chronic immune activation, and finally lead to CD4+ T-cell depletion and AIDS progression." (PMID 21118577, 2010). "The most recent data from cohort studies indicate that initiating cART at a CD4 cell count above 350 cells/μl may reduce the risk of AIDS and death." (PMID 20186270, 2010). "With respect to ART, one of the most important AIDS 2008 studies assessed the emergence of resistance-related mutations in Malawi sites that rely on CD4 counts and clinical symptoms to assess treatment response - because routine viral load monitoring remains too expensive." (PMID 19811670, 2009). "This “phenotypic switch” is strongly associated with rapidly declining CD4+ T cell counts and AIDS onset, yet its causes remain unknown." (PMID 19680436, 2009). "Type-1 human immunodeficiency virus (HIV-1), the etiologic agent of the acquired immunodeficiency syndrome (AIDS), causes a chronic disease characterized by a progressive loss of CD4+ T cells associated with other quantitative and qualitative alterations of the immune response." (PMID 19538732, 2009).
AIDS (continued). "C54 died of non-AIDS causes before the decline in CD4+ T cells necessitated anti-retroviral drugs." (PMID 18808677, 2008). "Thus, amongst those with recorded reasons for testing in the emergency department; roughly half were for symptoms consistent with AIDS (7/9 had a CD 4 count < 350/μL) and half were based on risk factors or patient request (6/10 had a CD4 count > 350/μL)." (PMID 18578881, 2008). "Third, the AIDS risk conveyed by the laboratory and genetic markers together, namely the CD4+ T cell count plus viral load plus GRG status, should exceed that conveyed by the two laboratory markers, especially during the early stages of infection when subjects have high CD4+ T cell counts." (PMID 18776933, 2008). "The preceding findings underscored that over and above the AIDS risk conveyed by the CD4 cell count and viral load, CCL3L1-CCR5 GRG status may serve as a unique parameter to identify HIV-infected individuals who are at an increased risk of developing AIDS." (PMID 18776933, 2008). "To validate that GRG status provided additional predictive value in the decision tree, we excluded GRG status from the analysis, and determined the risk and rate of progressing to AIDS for the four risk groups defined by the CD4 cell count and viral load cut-offs generated by CART." (PMID 18776933, 2008). "Our studies suggest enhanced fusogenicity of A-R5 Envs may contribute to CD4+ T-cell loss in subjects who progress to AIDS whilst harbouring R5 HIV-1 variants." (PMID 18076768, 2007). "CD4 counts from 350–500 cells/mm3 are associated with risks of ≤5% across all age and HIV-RNA strata, while the risk of progression to AIDS increases substantially at CD4 counts <350 cells/mm3, the greatest risk increase occurring as CD4 counts fall below 200 cells/mm3." (PMID 17502001, 2007). "Further highlighting the risk of AIDS in those with CD4 counts of 200–350 cell/mm3 (the current threshold for ART initiation), a four-fold risk increase can be seen between those with a HIV-RNA of 3000 copies/mL and those with ≥300 000 copies/mL, even within the same age bracket." (PMID 17502001, 2007). "Since average viral load remains more stable than CD4 T-cell count on the AIDS-risk scale, one may say that it exhibits more setpoint behavior." (PMID 17888148, 2007). "Enhanced fusogenicity of A-R5 Envs may contribute, at least in part, to CD4+ T-cell loss in subjects who progress to AIDS whilst harbouring R5 HIV-1 variants." (PMID 18076768, 2007). "Similarly, in two other studies, rapid progression of simian AIDS was accompanied by selection for CD4-independent variants." (PMID 17645788, 2007). "Similar findings were reported for simian immunodeficiency virus encephalitis 26, 32 and may in part reflect the general CD4+ T cell deficiency in AIDS." (PMID 17107594, 2006). "Furthermore, Nef-genes from AIDS patients were far more efficient in down-regulating CD4 than Nef-alleles from asymptomatic patients." (PMID 16107223, 2005). "However, we chose our cutoffs as CD4 levels < 350 cells/mm3 have been linked to AIDS and non‐AIDS‐related comorbidities and malignancies, including Kaposi syndrome, non‐Hodgkin and Hodgkin lymphomas, and lung and liver cancers, and have been previously used in immunodiscordant studies." (PMID 39868926, 2025). "The United States Centers for Disease Control and Prevention (CDC) defines acquired immunodeficiency syndrome (AIDS) as a cluster of differentiation 4 (CD4) cell count below 200/microL or the presence of any AIDS-defining condition regardless of CD4 cell count." (PMID 39958093, 2025). "Human immunodeficiency virus (HIV) is the causative agent of acquired immunodeficiency syndrome (AIDS), a condition where a severely immune-compromised state, due to decreased CD4+ T-lymphocyte population, allows various life-threatening opportunistic infections like Mtb to thrive." (PMID 40872312, 2025).